IL18 (interleukin 18)
Diseases named in the same sentence as IL18 in open-access papers (continued):
Sharing a sentence is not in itself a finding about the gene and the disease.
infection (continued). "Trim32−/− mice had a lower bacterial burden after Lm infection and survived significantly longer than wild-type (WT) mice, as well as lower serum levels of inflammatory cytokines TNF-α, IL-6, IL-18, IL-12p70, IFN-β, and IFN-γ at 1 day post infection (dpi) compared to WT mice." (PMID 37415157, 2023). "Interestingly, in the first phase (up to day 3 post-infection), the expression of NLRP3, IL-1β, and IL-18 was significantly upregulated in several organs before viremia was detectable in blood." (PMID 36800238, 2023). "IL-18 release following Δ6 Yptb infection occurred at a range of increasing doses, whereas WT Yptb failed to induce IL-18 release even at the highest doses." (PMID 37615436, 2023). "The data obtained show that M. furfur activates the inflammasome by inducing the expression of Il-1β, Caspase-1, IL-18, and NLRP-3 after 4 h of infection, while the simultaneous addition of L. plantarum totally inhibits this activation, bringing them back to the control values." (PMID 38132754, 2023). "In addition to NLRP3-derived IL-1β and IL-18, HMPV infection also leads to the over-expression of TNF and IL-6, which can worsen lung inflammation and disease outcomes following infection." (PMID 37508374, 2023). "This notion is also in agreement with our observation that infection with C. perfringens increased expression of IL-18 and IL-13 and not IL-12p40." (PMID 38164397, 2023). "It is also worth noting that only infection with the non-virulent strain T15 induced transcriptional upregulation of the pro-inflammatory cytokine IL18." (PMID 38276150, 2023). "In our study there was an important increase in pro-inflammatory cytokines (IL1β, IL6, TNFα, IL18, IL23) upon infection in all the groups analyzed in comparison with age-related control samples, as also seen for the immunoregulatory cytokines IL10 and IL17A, and for Th1 IFNγ NLF." (PMID 36561744, 2022). "Serum Th1 cytokines (e.g., interleukin (IL)-12, IL-18, interferon (IFN)- and tumour necrosis factor (TNF)) rise during the acute infection stage of the highly virulent RH strain, followed by mouse mortality 8 to 10 days post-infection." (PMID 35408644, 2022). "When microglial cells face a pathogen, for instance Streptococcus pneumoniae, a microorganism whose infections produce meningitis, they respond by assembling inflammasome NLRP3, activating caspase-1, secreting IL-1β and IL-18 and inducing cell death by pyroptosis." (PMID 35783102, 2022). "Gasdermin family is well known to play a vital role in pathogen infection, while more and more studies show that both pyroptosis and its related inflammatory cytokines IL-1β and IL-18 are the key factor in the process of non-infection related diseases." (PMID 35720396, 2022). "However, one mechanism employed by the inflammasome to protect against intratracheal infection is NLRP3/ASC secretion of IL-1β and IL-18." (PMID 35626718, 2022). "After infection, IFN-γ, mainly produced by NK cells and CD4+ T cells, stimulates macrophage activation, inducing high level of Th1 proinflammatory cytokines (e.g., IL-12, IL-2, IL-18, IL-27) and low levels of anti-inflammatory molecules." (PMID 36060742, 2022). "Importantly, we found that WT, Gbp1–/–, Gbp2–/–, Gbp3–/–, Gbp5–/–, and Aim2–/– BMDMs all released similar levels of IL-1β, IL-18 and LDH in response to infection with F. novicida in the presence of E. coli LPS." (PMID 35906252, 2022). "Of note, while there was increased cell apoptosis by TUNEL staining in both Il-22−/− and Il-18−/− mice during AIEC infection, the percentage of Caspase-3+ UEA1+ Goblet cells was not increased in Il-18−/− mice." (PMID 35169117, 2022). "Notably, peripheral-specific MAIT cells are activated in humans after infection with IAV, dengue virus, hepatitis C, and a series of acute infectious diseases, which drive the IL-18 dependent activation of MAIT cells and enhance the immune response." (PMID 35722312, 2022).
infection (continued). "In addition, the infection by SARS-CoV-2 triggers the inflammasome in macrophages, leading to IL-1β and IL-18 release in the lungs and contributing to pulmonary inflammation." (PMID 36083891, 2022). "In dogs, it has been reported that IL-18 has no prominent role in the infection outcome of the disease." (PMID 36443886, 2022). "By using microglia-derived cell lines, researchers observed that HIV promotes the synthesis of pro-IL-1β after 4 h post-infection and the release of this cytokine after 24 h; in agreement, brains of patients with AIDS showed high levels of IL-1β, IL-18 and caspase-1." (PMID 35783102, 2022). "During infection, NLRP3 is the primary producer of IL-1β and IL-18." (PMID 35626718, 2022). "The cytokines TNF-α, IL-6, IL-18, IFN-β, IFN-γ, and CSF3 produced by macrophages play important roles in the protection again pathogens by promoting phagocytosis and mediating the recruitment and activation of effector immune cells into the site of infection." (PMID 37431006, 2022). "IL-18 was constitutively expressed in NKB cells and robustly increased in response to infection." (PMID 33679805, 2021). "At days 1 and 3 post-infection, WT mice had significantly higher levels of brain IL-18 than NLRP3-/- and ASC-/- mice, demonstrating that ASC-dependent inflammasomes are also essential for IL-18 production during HSE." (PMID 33524073, 2021). "In this study, the relative expression levels of inflammatory cytokines TNFα, IL-8, IL-18, and IL-1β in IPEC-J2 cells along with the secretion of TNFα and IL-8 in the cell supernatant were significantly lower in the ΔhtpG infection group than those in the WT infection group." (PMID 34869065, 2021). "At very early stages of infection (12–48 h post infection) IL-18 transcription levels were not altered in birds challenged with C. jejuni when supplemented with L. fermentum during the first week of growth." (PMID 33477806, 2021). "During infections, APC-elicited IL-18 stimulates IFN-γ production by NK cells." (PMID 34305935, 2021). "Unlike the pattern observed in the liver, only splenic caspase-1, IL-1β, and GSDMD increased during S. mansoni infection; whereas levels of NLRP3 and IL-18 did not increase during infection." (PMID 34161342, 2021). "Infection with Salmonella can induce IL-23, IL-18, and IL-1β, but not IL-12, production in monocytes and type 1 pro-inflammatory macrophages." (PMID 34943999, 2021). "At 6 and 12 h post-infection, the mRNA expression levels of caspase-3, caspase-1, GSDMD, RIPK3, MLKL, NLRP3, IL-1β, and IL-18 were upregulated in RAW264.7 macrophages infected with either E. faecalis CA1, CA2, or OG1RF strains compared to the levels in the control group." (PMID 34513732, 2021). "TCR-independent heterologous immunity can arise through nonspecific activation by virus-induced cytokines such as IL-12 and IL-18 without TCR involvement whereby the second infection stimulates memory T cells from the first infection." (PMID 34421902, 2021). "Comparing levels of cytokines at the acute and convalescent phases, we found that concentrations of IL-1ra, IL-6, IL-18, and MCP-1 were relatively higher during the acute phase of infection, suggesting that these cytokines potentially play key roles in controlling O. tsutsugamushi infection." (PMID 34451491, 2021). "To test whether susceptibility could be explained by an overall deficiency in the intestinal immune response we analyzed gene expression for several infection-induced cytokines including TNF, IL-6, S100A, IL-18, and CXCL1." (PMID 32453761, 2020). "IL-18 induces the secretion of other pro-inflammatory cytokines, such as TNF-α, IL-1β and IL-8, which enhance the expansion, migration, and activation of neutrophils during infection." (PMID 33327639, 2020).
infection (continued). "Since studies had reported that NH/P68 induced enhanced cytokine gene expression or production in macrophages compared to a virulent isolate, cytokine gene (IL-1β, IL-6, IL-10, IL-12p40, IL-18, TNF-α) expression in moMΦ after NH/68 or 22653/14 infection were monitored over-time." (PMID 32178332, 2020). "In contrast, transcripts for other cytokines known to be secreted during DC maturation (tnf, il6) and after inflammasome activation (il1β, il18) were down modulated during infection, in accordance to the absence of secretion of these cytokines." (PMID 32582184, 2020). "Neutrophils released minimal amounts of IL-18 over 360 min, and this response did not change following infection with both 5448 or 5448AP, suggesting that neutrophils have no major role in IL-18 release over 360 min in vitro." (PMID 33585270, 2020). "Differential gene expression in implanted CT26 tumors treated with mVG161 compared to equivalent tumors injected with VG160 revealed that infection with mVG161 bearing IL-12, IL-15, and IL-15RA transgenes powerfully stimulates a prototypical Th1 immune response (e.g., IFN-γ, TNF, and IL18)." (PMID 33182232, 2020). "While HSV-1 infection of the WT, ΔAIM2, and ΔIFI16 THP-1 cells led to significant IL-18 production, infection of ΔNLRP3, Δcaspase-1, and ΔASC cells resulted in levels of IL-18 that were not significantly different from mock infection." (PMID 32101570, 2020). "In the caecal tonsil of S. Enteritidis-infected chickens, an inflammatory profile was evident throughout the infection period with significantly increased expression of IFN-γ mRNA at days 2, 4, and 5 pi, IL-12 (day 2), IL-18 (day 4) and IL-17F (days 4 and 5) compared to uninfected controls." (PMID 33076485, 2020). "In rodents, the activation of caspase-1 provoked the release of IL-18 which, in turn, induced IFN-γ to prime caspase-11 activity, whereas caspase-4 transgenic mice did not necessitate IFN-γ priming upstream of caspase-4 to control the infection." (PMID 33329561, 2020). "Cath1 and Cath2 stimulate PBLs to upregulate Il-8, but not Il-1β and interleukin 18 (Il-18), in Atlantic salmon at five and eight h post-infection (hpi)." (PMID 32824728, 2020). "Lower IL‐1β and IL‐18 levels in RH‐CHIKV infection may lead to dampened NLRP3 pathways, resulting in reduced joint inflammation during acute phase of infection." (PMID 31015278, 2019). "By contrast, IL-18 secretion was unaltered during infection and had no influence on the pathogenicity of HMPV in mice." (PMID 30964929, 2019). "Similar to the cytokine regulation observed in the mouse lung, IL-18 transcripts did not change upon AB14 (H5N1) infection when compared to the uninfected control." (PMID 30813415, 2019). "The amniotic fluid concentrations of some inflammasome mediators (CASP1, IL1B, NLRP3, and IL18) are greater in women who have spontaneous preterm or term labor with intraamniotic infection/inflammation than in those without this clinical condition." (PMID 30935390, 2019). "The influence of the presence or absence of IL-18 is thought to depend on the mouse strain and the infectious dose of L. monocytogenes used for infection." (PMID 30717382, 2019). "It has previously been shown that S. Typhimurium infection causes a rapid expression of chemokines and pro-inflammation cytokines, including IL12 and IL18, in the intestinal tissues until 4 days post-infection, but not in the spleen samples." (PMID 31998655, 2019). "Additionally, IL18BP, an antagonist of IL-18 (an important member of the IL-1 super family of cytokines), was also up-regulated after infection, supporting the observation that ASFV infection suppresses IL-1 and IL-18 signaling." (PMID 31725732, 2019). "In addition, at 28 weeks’ post-infection, human proinflammatory cytokines such as interferon gamma (IFN-γ), monocyte chemoattractant protein 1 (MCP-1) and interleukin 18 (IL-18) were significantly increased in the plasma of HIL mice." (PMID 31213010, 2019).
infection (continued). "Recognition of T. cruzi by the innate and adaptive immune cells trigger the production of cytokines, such as IL-1β, IL-18, IL-6, TNF, and IL-10 during the acute phase of infection which exert profound effects in the killing of parasites and in the modulation of inflammation." (PMID 29774028, 2018). "Plasma IL-18 (an IL-1 superfamily protein produced by activated macrophages) was elevated in SIV-infected RM-Ch during acute infection, but returned to baseline during the chronic phase of infection." (PMID 29391069, 2018). "Therefore, IL18 and RFX1 were more likely to be regulated by the poorly represented miR-346 in our infection model." (PMID 29867904, 2018). "The current study selected elderly patients with normal renal function to accept spinal anesthesia and excluded the patients with infection, malignant tumors, and other factors that may affect the level of NGAL and IL-18 in plasma and urine." (PMID 28222674, 2017). "RT-qPCR analysis revealed that at 6 h of infection, hyphae and, to a lesser extent, conidia induce Il1b and Tnfa, but not il18 transcripts in BMDMs." (PMID 29209318, 2017). "Unlike tight regulation to control infection spread in lymphoid organs, this local interface between IL-18-expressing and responder cell is increasingly supported in lung as disease progresses, increasing its potential to increase tissue damage via IFNγ." (PMID 28830544, 2017). "IL-18 was lower on day 2 than at baseline in asthmatics and significantly lower in asthmatic compared to normal subjects on day 4 and IL-4 and CCL13/MCP-4 were also decreased after infection in asthmatics on days 5 and 7 and day 2 respectively." (PMID 28373098, 2017). "After 6 h of hCFs infection with wild-type PAO1 and PA14, significant levels of TLR4, TLR5, NLRC4, native form of caspase-4 and IL-1β and IL-18 mature-formed proteins were detected by western blot with quantification of protein densitometry ratios relative to endogenous β-actin." (PMID 28469996, 2017). "However, lower expression levels of CXCLi2, IL-18 and IFN-γ were observed on day 4 post infection particularly in the bursa of NDV AF2240 infected chicken." (PMID 28569155, 2017). "The mean titer of IL-18 of the infection mortality group was higher than the non-infection mortality group (947.92 ± 236.56 pg/ml vs. 731.23 ± 158.24 pg/ml, p = 0.001)." (PMID 28474577, 2017). "Therefore, the expression of IL-1β, IL-18, NLRP3, Caspase-1, ASC, and Syk mRNA was characterized in lung macerates of WT, Nlrp3−/−, Casp1/11−/−, and Asc−/− mice at week 4 after infection." (PMID 28740491, 2017). "Casp1Null BMDMs did not secrete IL-1β and IL-18 in response to infection by E. coli and C. rodentium or transfection of LPS." (PMID 28345580, 2017). "Thus, the reduced level of mRNA for IL-18 and IFN-γ in the late stage of infection probably correlates to the decline in the protective efficacy of the MDV vaccine." (PMID 29018431, 2017). "In comparison with wild-type bacteria, infection with the complemented PA14 ΔflgK pUCP19-flgK and PA14 ΔpopB pUCP19-popB strains restored to varying degrees the protein levels of TLR4, TLR5, NLRC4, caspase-4 and mature IL-1β and IL-18." (PMID 28469996, 2017). "Besides, the IL-1β expression level at 6, 24 and 48 hpi, and IL-18 expression level at 6 and 24 hpi were all significantly increased during SCAU-HN06 infection." (PMID 29245947, 2017). "Following infection of differentiated THP-1 macrophages with an adherent and invasive C. concisus strain, genes encoding IL-23 and IL-18, but not IL-22, were regulated as assessed by transcriptomic and proteomic analyses." (PMID 27385977, 2016). "This is in line with a direct regulatory function of IL-18 during acute infection rather than a homeostatic imbalance in the genetically deficient animals." (PMID 27341123, 2016). "In the absence of Nlrp3 or Aim2, the macrophage IL-18 response to Ft LVS or SchuS4 infection was reduced by about 50%." (PMID 27926940, 2016).
infection (continued). "Thus, levels of IL-18 in plasma and expression of IL-18R on MAIT cells in vivo are upregulated during the acute phase of infection, especially in those patients suffering from DHF." (PMID 27337592, 2016). "In vitro infection of DCs with HIV also led to a defective production of IL-12 and IL-18." (PMID 27821119, 2016). "IL-1β and IL-18 play an important role in local immunity and in the activation of lymphocytes and macrophages in the antiviral response, while IL-18 is mainly involved in coordinating IFN-γ production from NK cells and T cells at the early and late phases of infection, respectively." (PMID 24701032, 2014). "In the absence of LPS priming, Type II strain-infected BMDMs did not produce IL-1β (data not shown), but low levels of IL-18 were measurable by 6 h (PRU) and 24 h (76K) of infection in an NLRP1 variant-dependent manner." (PMID 24626226, 2014). "During S. Typhimurium infection IL-1β is reported to be critical for the intestinal phase of the disease, while IL-18 is important for resistance to systemic infection but not the early gastrointestinal phase of infection." (PMID 25115174, 2014). "Nlrp3−/− mice, however, expressed equal plasma levels of IL-18 after infection at all time points when compared to WT mice, indicating that IL-18 production is independent of NLRP3 during experimental S. Typhimurium infection in vivo." (PMID 25115174, 2014). "T-cells, B-cells, and dendritic cells did not secrete any appreciable IL-18 when cultured with pre-infection or V plasma." (PMID 24788318, 2014). "For example, a recent study showed a role for NLRP12 in inflammasome formation and IL-1β/IL-18 maturation in response to a subcutaneous infection with a genetically attenuated strain of Yersinia, but not other activators that engage the NLRP3 inflammasome." (PMID 23577168, 2013). "To clarify how h1 deletion affects caspase-1 activation upon infection by V. parahaemolyticus, we examined the amounts of released IL-1β and IL-18 from the infected BMMs with or without LPS pretreatment." (PMID 23357873, 2013). "In BMDMs with non-infected control (NI) and with the iacP fljB fliC mutant infection, the levels of cytokines IL-18 and IL-1β were not detectable." (PMID 24069357, 2013). "While for some authors interleukin-6 (IL-6) and IL-18 are markers of active disease or asymptomatic infection; respectively, for others IL-6 and IL-18 have no determinant role." (PMID 21845197, 2012). "While we did not observe any increase in the pro-IL-18 mRNA in the JEV treated brain samples up to 7 days after infection, we observed a significant increase in IL-18 protein levels in these brain samples." (PMID 22393394, 2012). "During infection in the CNS, JEV initiates a potent inflammatory response including microglial activation which subsequently results in the production of several pro- and anti-inflammatory cytokines including IL-1β and IL-18." (PMID 22393394, 2012). "Moreover, we indicated nDens of 2 genes induced and 2 genes repressed in all infection performed and nDens of all genes discussed above (IL-1β, IL-6, IL-12, TNF-α, IL-10, ADAM19, CCR7, CCL20 and IL-18)." (PMID 21436989, 2011). "CAPE-treated wild-type and TLR2−/− macrophages did not undergo cell death or secrete IL-18 after F. novicida infection." (PMID 21698237, 2011). "We infected P2X7R−/− macrophages with wild-type F. novicida and found that the levels of cell death and IL-18 secretion (data not shown) were similar to the levels measured in infected wild-type macrophages at 7 h post-infection." (PMID 21698237, 2011). "High level IL-12p40 production in ΔROP16 infection was dependent on the host cell adaptor molecule MyD88, but surprisingly was independent of any previously recognized T. gondii triggered pathway linking to MyD88 (TLR2, TLR4, TLR9, TLR11, IL-1ß and IL-18)." (PMID 21931552, 2011).